YY1 (YY1 transcription factor)
Diseases named in the same sentence as YY1 in open-access papers (continued):
Sharing a sentence is not in itself a finding about the gene and the disease.
prostate carcinoma (continued). "In summary, YY1 is a recognized prostate cancer driver and different complexes in which YY1 takes part can induce activation or repression of gene expression, including also AR-YY1-mediated PSA transcription, which we found is also regulated by HMGB1 and HMGB2 silencing." (PMID 31694235, 2019). "Likewise, an inverse correlation in the expression of YY1 and miR-146a has been reported in prostate cancer." (PMID 31824839, 2019). "Induction of RKIP expression inhibits the activation of signal transducer and activator of transcription 3 (STAT3), NF-κB pathway, and downstream Yin Yang 1 (YY1) as well as antiapoptotic gene products, causing induction of apoptosis in breast and prostate cancer cells." (PMID 25147739, 2014). "We postulated that YY1 may be a potential biomarker in prostate cancer for patients' stratification as well as a novel target for therapeutic intervention." (PMID 25053986, 2014). "The present findings suggested that DR5 and YY1 expression levels may serve as progression biomarkers for prostate cancer." (PMID 25174820, 2014). "Interestingly, variations on the expression levels of YY1 mRNA in prostate cancer were reported by different investigators." (PMID 25053986, 2014). "We also believe that the findings reported in prostate cancer may be also found in many other cancers and, therefore, therapeutic inhibitors of YY1 may be of general use for many cancers." (PMID 25053986, 2014). "YY1 expression is upregulated in human prostate cancer cell lines and tissues." (PMID 25053986, 2014). "Therefore, YY1 is proposed to be a therapeutic target for intervention as well as a potential prognostic biomarker in prostate cancer." (PMID 25053986, 2014). "Our results also suggest multiple roles for YY1 in prostate cancer which may contribute to disease progression by modulation of genes such as PSCA." (PMID 22536409, 2012). "The earlier description of regulation of the PSA promoter by an YY1-AR complex, together with the present work, suggests that YY1 may influence prostate cancer progression by regulation of at least two prostate cancer genes." (PMID 22536409, 2012). "Interestingly, high levels of YY1 are observed in high-grade prostate cancer, but prostate tumors with areas of low YY1 expression show a high rate of recurrence." (PMID 19566924, 2009). "YY1 could also promote epithelial‐mesenchymal transition in prostate cancer." (PMID 32557953, 2020). "In addition, it was previously demonstrated that YY1 may transcriptionally repress DR5 expression in prostate cancer cell lines." (PMID 25174820, 2014). "Thus, YY1 has a role in epigenetic regulation of prostate cancer genes." (PMID 22536409, 2012). "Thus, changes in PSCA expression levels in prostate cancer may at least partly be affected by cellular levels of YY1." (PMID 22536409, 2012). "Furthermore, knockdown of YY1 in prostate cancer cell lines increased endogenous PSCA message, suggesting that changes in PSCA message levels during prostate cancer progression may be at least partially regulated by YY1." (PMID 22536409, 2012). "We demonstrate that, when tested in vitro, using nuclear extracts from breast and prostate cancer cell lines, the YY1 protein was able to bind the non-risk allele (G) of 378854, a perfect proxy for the initially reported prostate cancer signal rs620861, more strongly than the risk allele." (PMID 21814516, 2011). "In conclusion, the marine natural product pyripyropene O induces apoptosis of prostate cancer PC-3 cells by targeting the YY1/DR5 axis, resulting in an anti-prostate cancer effect." (PMID 40422804, 2025). "Concerning PDT-induced NO-mediated cytoprotective molecular mechanisms, a further in vitro study on prostate cancer PC3 and LNCaP cells revealed key pathways in the activation of pro-survival/anti-apoptotic NF-κB and Yin Yang 1 (YY1)." (PMID 39996790, 2025).
prostate carcinoma (continued). "Lowering YY1 expression reduces PFKP expression and tumor cell metabolism while inhibiting mitosis and promoting apoptosis of prostate cancer cells." (PMID 37444616, 2023). "We find that MBNL1-AS1 has been reported to inhibit the progression of prostate cancer by sponging miR-181a-5p and regulating PTEN/PI3K/AKT/mTOR signaling and PTEN signaling happens to be regulated by PLK1, PAF, YB-1, TWIST, YY1, KLF4, and SALL4." (PMID 35518784, 2022). "YY1 inhibition has previously been shown to upregulate DR5 expression and enhance rTRAIL sensitivity in prostate cancer and B-non-Hodgkin's lymphoma cells." (PMID 34597666, 2021). "Previous studies have shown that miR186 targeted IGF-1R in glioma, and Yin Yang 1 (YY1) and cyclin dependent kinase 6 (CDK6) in prostate cancer." (PMID 32082999, 2020). "While, YY1 largely acted as a tumor promoter in prostate cancer, upon interacting with SFMBT2 (Scm-like with four mbt domains 2), YY1 acts both as a tumor promoter and suppressor in prostate cancer." (PMID 31824839, 2019). "In case of LNCaP, SFMBT2 interacts with YY1 and represses MMP2, MMP3, and MMP9 and inhibits invasion and migration of prostate cancer cells, and illustrating both pro and anti-role of YY1 in prostate cancer growth." (PMID 31824839, 2019). "It was shown that YY1 binds to XAF1 promoter and thereby inhibits its expression in prostate cancer cell lines in a HDAC1 dependent mechanism." (PMID 31824839, 2019). "YY1 positively regulates expression of PSCA (Prostate stem cell antigen) via which it is believed to contribute to disease progression and metastasis in prostate cancer." (PMID 31217904, 2019). "Our preliminary findings have further identified an additional oncogene and NF-κB target, Yin Yang 1 (YY1), to play a vital role in prostate cancer metastasis, since YY1 silencing in metastatic prostate cancer cell lines was able to inhibit TGFβ-induced EMT." (PMID 30149591, 2018). "Our approach has yielded 11 transcription factors that show strong cancer-specific transcriptional activation of targets, including the novel candidates KAT2A and TRIM28, alongside established drivers of prostate cancer MYC, ETS1, GABP and YY1." (PMID 28592290, 2017). "SFMBT2 interacts with YY1 and regulates cell growth through repression of the HOXB13 gene in DU145 prostate cancer cells." (PMID 27340776, 2016). "For example, the overexpressions of YY1, SOX2 and OCT4 in prostate cancer cell lines have been reported." (PMID 27225481, 2016). "Of the several transcription factors identified, a few namely E2F1, MYC, YY1, CHD1 and SMARCA4 which have been shown to express in prostate cancer tissues are of particular interest." (PMID 25938433, 2015). "Our recent findings have identified one transcription factor, namely, Yin Yang 1 (YY1), that is overexpressed in prostate cancer and YY1 was found to regulate tumor cell growth and drug resistance." (PMID 25053986, 2014). "To determine interaction of YY1 with the PSCA promoter in vivo, we conducted chromatin immuno-precipitation analysis (ChIP) using human and murine prostate cancer cell lines." (PMID 22536409, 2012). "The transcription factor Yin Yang 1 (YY1) is expressed in normal tissues and is up-regulated in various cancers including prostate cancer, with positive and negative regulatory effects on gene expression." (PMID 22536409, 2012). "Our group has previously reported a variety of marine natural products with anti-prostate cancer properties, and no marine natural products targeting the YY1/DR5 signaling axis have been identified." (PMID 40422804, 2025). "Further studies also showed that pyripyropene O induced apoptosis of prostate cancer cells and that pyripyropene O promoted apoptosis of prostate cancer cells by activating the expression and function of DR5 through binding to the transcription factor YY1." (PMID 40422804, 2025).
prostate carcinoma (continued). "Previous studies have shown that YY1 regulates IL6 expression in a variety of conditions, including LPS-stimulated BV2 microglial cells, and in vivo models for rheumatoid arthritis and prostate cancer." (PMID 40143084, 2025). "Additionally, YY1 represses expression of death receptor 5 (DR5) and Fas, thereby conferring resistance to TRAIL and FasL induced apoptosis in prostate cancer cells." (PMID 31217904, 2019). "YY1 represses the tumor suppressor XAF1 and thereby promotes prostate cancer growth." (PMID 31824839, 2019). "Elevated YY1 expression is correlated with the development of PIN and advanced prostate cancer." (PMID 25174820, 2014). "Although we cannot exclude the possibility that other mutations acquired by PC-3 cells may contribute to the downregulation of PSCA by YY1, our data strongly suggest that YY1 may inhibit PSCA expression in advanced prostate cancer." (PMID 22536409, 2012). "Elevated YY1 expression is correlated with development of PIN and advanced prostate cancer." (PMID 22536409, 2012). "Thus, interaction of YY1 with the PSCA promoter occurs in vivo, and has the potential to modulate PSCA expression in human and murine prostate cancer cell lines." (PMID 22536409, 2012). "To determine whether YY1 also modulates human PSCA expression, we determined the effect of YY1 knockdown in an androgen-dependent human prostate cancer cell line, LNCaP, and an androgen-independent human prostate cancer cell line, PC-3." (PMID 22536409, 2012). "YY1 and HDAC4 complex represses HOXB13 gene in AR negative prostate cancer cells." (PMID 31824839, 2019).
lung carcinoma (50 papers, 2009 to 2025). "In lung cancer carrying Kras mutations, it has been demonstrated that the YY1 transcription factor is a crucial mediator between the mutated isoform of Kras and Shh signaling." (PMID 38339244, 2024). "Both of these TFs have been reported to be involved in cancer development and YY1 is a dual function TF and has been implicated as a major driver of many cancers including lung cancer." (PMID 35138370, 2022). "YY1 has been implicated in the metastatic progression of lung cancer cells due to its regulation of the putative metastasis suppressor HLJ1." (PMID 19566924, 2009). "YY1 had been reported as a known lung cancer associated gene." (PMID 26859295, 2016). "For example, a recent study showed that HDAC2, YY1, and c-Myc participate in lung cancer growth and development." (PMID 41009346, 2025). "In lung cancer, YY1 overexpresses the non-coding RNA MCM3AP-AS1, which promotes cancer progression by binding to and degradation of miR-340-5p, a negative regulator of angiogenesis." (PMID 38339244, 2024). "Taken together, YY1 was ubiquitously expressed and exhibited anticipated fluctuation following targeted treatment in lung cancer patients." (PMID 39604408, 2024). "First, immunohistochemical interrogation of 89 EGFR-mutant, 51 KRAS-altered, and 46 ALK-rearranged lung cancer specimens unveiled that YY1 was ubiquitously expressed in malignant cells at an elevated level relative to the normal epithelium." (PMID 39604408, 2024). "The same group identified the Kras/YY1/ZNF322A/Shh transcriptional axis as part of an important mechanism underlying neo-angiogenesis and migration of lung cancer cells in in vitro/vivo models." (PMID 38339244, 2024). "As indicated in the Results section, we evaluated those targets in our experimental system and found that GLUT1, NRP1, YY1, and Wnt5a were effectively inhibited by the miRNA in lung cancer cells." (PMID 38672608, 2024). "This interaction reduces the miRNA silencing activity toward its downstream targets, i.e., the mRNAs coding for GLUT1, NRP1, YY1, and Wnt5a, thus contributing to oncogenic pathways driving lung cancer." (PMID 38672608, 2024). "At the protein level, immunoblotting assays illustrated that YY1 was readily detectable in a wide spectrum of oncogene-driven lung cancer cell lines, as well as in most primary tumor samples regardless of EGFR mutation." (PMID 39604408, 2024). "For example, YY1 acts as a prognostic biomarker after its repression of the Raf kinase inhibitory protein (RKIP) in lung cancer." (PMID 37686541, 2023). "On the other hand, limiting ROS production and inhibiting YY1 in lung cancer cells prevented MCT-1-induced cell invasiveness and the EGFR-MnSOD signaling pathway." (PMID 37081988, 2023). "Recently, YY1 was shown to repress RKIP in lung cancer, suggesting a potential link between these two genes." (PMID 37894300, 2023). "According to these results, disruption of the Kras/YY1/ZNF322A/Shh transcriptional axis encourages lung cancer neoangiogenesis and cancer development." (PMID 37081988, 2023). "Not only protein-encoding genes but YY1 can target the transcription of lncRNA MCM3AP-AS1, further targeting the miR-340-5p/KPNA4 axis stimulated lung cancer angiogenesis and progression." (PMID 37081988, 2023). "For example, a recent study demonstrated that YY1 negatively regulates RKIP expression in lung cancer." (PMID 37894300, 2023). "On the other hand, miR-193a-5p downregulation leads to YY1 overexpression in endometrial and lung cancers due to its involvement in migration and metastatic cancer activities." (PMID 37686541, 2023). "Anterior studies have shown that YY1 can enhance the process of carcinoma, such as lung cancer, and repress mammary formation." (PMID 36952101, 2023). "The signal pathways related to lung cancer progression can upregulate the expression of YY1 in lung cancer, while the overexpression of YY1 can lead to cancer progression by positively regulating the expression of many oncogenes." (PMID 35359580, 2022).
lung carcinoma (continued). "The high expression of the transcription factor Yin Yang 1 (YY1) has been shown to positively correlate with large tumors, poor differentiation, and metastasis to lymphoid nodules in patients with lung cancer." (PMID 35682855, 2022). "A previous study reported that high expression of MCTS1 induced the generation of ROS, which caused YY-1/EGFR/MnSOD signaling amplification and cancer cell invasion in lung cancer." (PMID 35295953, 2022). "More specifically, YY1 can transcriptionally regulate COX-2 and overexpression of the COX-2 gene is linked to the pathogenesis of various types of cancer, including lung cancer." (PMID 35682855, 2022). "Our data suggested that YY1 functioned as a tumor suppressor gene and miR-34a blocked lung cancer progression partly via increasing YY1 expression." (PMID 33796457, 2021). "We further explored the regulatory mechanisms between miR-34a and its downstream CDK6, PTEN, and YY1 to try to find the specificity and similarity of lung cancer in tin miners in Gejiu County and farmers in Xuanwei County compared to other NSCLC regions." (PMID 33796457, 2021). "This study provides new mechanistic insights into how oncogenic Kras-induced YY1/ZNF322A transcriptional axis promotes lung cancer progression." (PMID 32929330, 2020). "In this study, we identify Kras/YY1/ZNF322A/Shh transcriptional axis as part of an important mechanism underlining neo-angiogenesis and lung cancer metastasis." (PMID 32929330, 2020). "Collectively, these results supported that ZNF322A upregulation mediated by Kras/YY1 axis promotes proliferation and migration of lung cancer cells." (PMID 32929330, 2020). "YY1 has been reported to induce lncRNA MCM3AP-AS1 overexpression in lung cancer, and overexpressed MCM3AP-AS1 promoted angiogenesis via targeting KPNA4 through shared miR-340-5p." (PMID 32272940, 2020). "Since we unveiled YY1 as a crucial mediator of Kras mutation-driven transcription of ZNF322A, we analyzed the role of YY1 in lung cancer cell proliferation and migration." (PMID 32929330, 2020). "YY1 is a highly multifunctional transcription factor that promotes cell proliferation and invasion in lung cancer cells, and EMT in H1155 cells." (PMID 31867044, 2019). "Therefore, YY1 overexpression in lung cancer might suggest an association of these transcription factor in driving tumorigenic processes and the acquisition of stem-like characteristics in early stages of lung cancer." (PMID 31867044, 2019). "The KM plotter analysis for the transcription factors identified during the present study revealed a statistically significant association between the expression levels of YY1 and NR4A2 with the survival of lung cancer patients." (PMID 31867044, 2019). "YY1 expression has been shown to be elevated in lung cancer tissues and YY1 has been shown to play a key pro-tumorigenic role in lung cancer." (PMID 31824839, 2019). "Further, the tumor suppressive role of YY1 in lung cancer was also evidenced by the finding that YY1 binds to the promoter of tumor suppressor microRNA-520c-3p and enhances its expression." (PMID 31824839, 2019). "Conversely, restricting ROS generation and/or targeting YY1 in lung cancer cells effectively inhibits the EGFR-MnSOD signaling pathway and cell invasiveness induced by MCT-1." (PMID 28394354, 2017). "Clinical evidence further confirms that high expression of MCT-1 is associated with an increase in YY1, EGFR and MnSOD expression, accompanied by tumor recurrence, poor overall survival and EGFR mutation status in patients with lung cancers." (PMID 28394354, 2017). "MCT-1 expression was largely positively associated with YY1 (Phi coefficient +0.27, P=0.003), EGFR (Phi coefficient +0.43, P<0.001) and MnSOD (Phi coefficient +0.59, P<0.001) in all stages of lung cancers." (PMID 28394354, 2017).